FPR1 (formyl peptide receptor 1)
Diseases named in the same sentence as FPR1 in open-access papers (continued):
Sharing a sentence is not in itself a finding about the gene and the disease.
Stroke (6 papers, 2008 to 2023). Sudden impairment of blood flow to a part of the brain due to occlusion or rupture of an artery to the brain. "Indeed, FPR1 signaling is important in activating the NLRP3 inflammasome as evidenced by reduced inflammation, leukocyte infiltration, and tissue damage in Fpr-1 KO mice, as well as limiting neuroinflammation following stroke." (PMID 35603196, 2022). "Lastly, we predicted 53 potential drugs that may exert neuroprotective effects in early stroke by targeting 5 genes (STAT3, MMP9, AQP9, SELL, FPR1)." (PMID 37180174, 2023). "However, for most predicted drugs, especially FPR1 inhibitors, direct experimental evidence for their pharmacological effect on stroke is currently lacking." (PMID 37180174, 2023). "FPR1 may be proved to be a reasonable target to induce neuroprotection in humans in future studies because FPR1 is expressed in activated cells 9 and blocking FPR1 may not affect baseline functions of monocytes and macrophages, a desirable situation for patients with stroke." (PMID 35547761, 2022).
basophilic leukaemia (5 papers, 2015 to 2022). "[SRSRY] inhibits FPR1-mediated cell migration and prevents both the internalization and ligand-uptake of FPR1 in rat basophilic leukemia RBL-2H3 cells which constitutively express human FPR1." (PMID 35158766, 2022). "We have recently found that the cyclized peptide SRSRY ([SRSRY]) inhibits in a dose-dependent manner directional migration of rat basophilic leukemia RBL-2H3/ETFR cells expressing high levels of constitutively activated FPR1." (PMID 27323409, 2016). "RERF inhibits in a dose-dependent manner the directional migration of rat basophilic leukemia RBL-2H3/ETFR cells expressing high levels of FPR137 by preventing the uPAR/FPR1 interaction and, consequently, agonist-triggered FPR1 activation." (PMID 28465589, 2017). "In rat basophilic leukaemia RBL-2H3/ETFR cells expressing high levels of constitutively activated FPR1, the cyclic SRSRY peptide ([SRSRY]) blocks FPR1 mediated cell migration by interfering with both internalization and ligand-uptake of FPR1." (PMID 25938482, 2015).
cervical cancer (5 papers, 2019 to 2026). A primary or metastatic malignant neoplasm involving the cervix. "Among these, FPR1 participates in tumorigenicity of human cervical cancer cells via activation of immune cells induced by N-formyl peptide." (PMID 33968933, 2021). "As shown in our previous study, FPR1 is overexpressed in cervical cancer (Guangming Cao's data are shown in another paper under review)." (PMID 31772669, 2019). "In our previous study, we found that FPR1 is upregulated in cervical carcinoma tissues compared with peritumoral tissues by use of tissue microarray analysis (Guangming Cao's data are shown in another paper under review)." (PMID 31772669, 2019). "In this study, we investigate the potential role of FPR1 in cervical cancer immunotherapy." (PMID 31772669, 2019). "In this study, we developed a novel immunotherapeutic peptide by linking the Mycobacterium tuberculosis (MTB) heat shock protein 70 (Hsp70) functional peptide to the extracellular domain of FPR1, a protein overexpressed in cervical cancer, to obtain an MTBHsp70-exFPR1 fusion protein." (PMID 31772669, 2019). "Thus, FPR1 is a potent therapeutic target that can be used in cervical cancer immunotherapy." (PMID 31772669, 2019).
colon cancer (5 papers, 2017 to 2024). "It should be interesting to examine whether there is an exacerbated malignant phenotype of colon cancer co-expressing both FPR1 and FPR2 receptors." (PMID 28724995, 2017). "The expression of FPR1 in GC tissues is higher than that in normal tissues, which is closely related to the survival time of patients 50, and FPR2 is also highly expressed in endometrial and colon cancer." (PMID 38817876, 2024).
Listeria monocytogenes infection (5 papers, 2012 to 2023). "FPR1 and FPR2 are crucial for bacterial immune defense, as FPR1- and FPR2-deficient mice are characterized by increased susceptibility to Listeria monocytogenes infection and meningitis caused by Streptococcus pneumoniae, in comparison to wild-type mice." (PMID 37512874, 2023). "The first evidence for the importance of Fpr1 in Listeria infection was provided in an early study which demonstrated increased susceptibility of Fpr1 KO mice to infection." (PMID 32038501, 2020). "Studies have shown that Fpr2 confers protection against sepsis-mediated tissue damage in mice and both Fpr1 and Fpr2 are indispensable for mouse resistance to Listeria infection." (PMID 32038501, 2020).
Obesity (5 papers, 2022 to 2025). Accumulation of substantial excess body fat. "The aim of the work was to investigate NADPH-oxidase-dependent generation of reactive oxygen species (ROS) initiated though membrane formyl peptide receptors (Fpr1, Fpr2) in bone-marrow granulocytes of obesity-resistant mice (ORM) fed high-fat diets (HFD)." (PMID 36984693, 2023). "We analyzed the generation of reactive oxygen species (ROS) initiated though membrane formyl peptide receptors (Fpr1, Fpr2) in bone-marrow granulocytes of obesity-resistant mice (ORM)." (PMID 36984693, 2023). "In mice with obesity induced by a high-fat diet (HFD), an increase in fMLP levels, particularly within the gastrointestinal tract, coincided with upregulated FPR1 expression, notably in the ileum and colon." (PMID 40733247, 2025). "Our findings that primary adipocytes express both fpr1 and fpr2, and direct addition of WKYMVm into primary adipocytes effectively modulates the expression of genes in lipid metabolism suggest that WKYMVm may act on primary adipocytes, resulting in the improvement of lipid metabolism in obesity." (PMID 37603580, 2023).
pneumonia (5 papers, 2015 to 2026). An acute, acute and chronic, or chronic inflammation focally or diffusely affecting the lung parenchyma, caused by an infection in one or both of the lungs (by bacteria, viruses, fungi, or mycoplasma.). "To fully understand the effect of SCIMP on pneumonia, we utilized chemotaxis assays, Scimp-deficient mice, Fpr1/2-deficient mice, and a lethal ALI murine model to elucidate the role of the macrophage-SCIMP-FPR-neutrophil axis in pneumonia." (PMID 38263143, 2024). "Pathway readouts supported actions on complementary axes (TLR4-IRAK1, STING1-IFN-β, FPR1-AKT, CASP8, and HDAC2-H3K9ac), providing a mechanistic basis for their collective protection against pneumonia." (PMID 41484909, 2026). "The lack of Fpr1 and Chil1 led to a higher mortality rate in murine models of pneumococcal meningitis and pneumonia, respectively." (PMID 35795182, 2022).
rheumatoid arthritis (5 papers, 2011 to 2022). A chronic, systemic autoimmune disorder characterized by inflammation in the synovial membranes and articular surfaces. "In rheumatoid arthritis (RA), WKYMVm stimulates IL-10 production by acting on FPR1 which is expressed on the surface of mature dendritic cells (DCs)." (PMID 36120322, 2022).
Alzheimer disease (4 papers, 2012 to 2025). A progressive, neurodegenerative disease characterized by loss of function and death of nerve cells in several areas of the brain leading to loss of cognitive function such as memory and language. "In 12 month old APP/PS1 Alzheimer’s disease (AD) transgenic mice, mRNA transcripts and Fpr1 protein expression were upregulated." (PMID 36556373, 2022).
astrocytoma (4 papers, 2010 to 2019). "Targeting FPR1 with a specific antagonist was found to reduce astrocytoma cell motility and activation, thus prolonging the survival of tumour-bearing mice." (PMID 31170199, 2019). "Activation of FPR1 in human astrocytoma cell lines promotes motility, growth and angiogenesis." (PMID 31170199, 2019).
atherosclerosis (4 papers, 2022 to 2024). A disease characterized by the build-up of fatty material and calcium deposition in the arterial wall resulting in partial or complete occlusion of the arterial lumen. "In atherosclerosis, FPR1 exacerbates plaque formation and instability by promoting the recruitment and activation of inflammatory cells." (PMID 39700090, 2024). "Overexpression of CXCL3, GK, FPR1, and LST1 was advanced recognition and intervention factors for unstable plaques, which might become targets for atherosclerosis rupture prevention." (PMID 36187340, 2022).
Hepatic fibrosis (4 papers, 2020 to 2025). The presence of excessive fibrous connective tissue in the liver. "Collectively, these data demonstrate that FPR-1 is not required for the development of hepatic fibrosis." (PMID 32102985, 2020). "Importantly, fibrosis, as measured histologically and biochemically, was comparable between C57BL/6 and fpr1–/– mice, suggesting that FPR-1 is not required for initiation or progression of liver fibrosis in response to CCl4 challenge." (PMID 32102985, 2020).
Hyperglycemia (4 papers, 2012 to 2020). An increased concentration of glucose in the blood. "Finally, cytofluorimetric analysis of FPR1 expression in WS1 cells showed that hyperglycemia conditions could slightly increase cell surface expression of this receptor." (PMID 23029153, 2012). "In order to verify whether glucose levels would affect the extent of expression of FPR1, we assessed the FPR expression in WS1 cells by cytofluorimetric analysis, and we found that hyperglycemia conditions could slightly increase cell surface expression of FPR1 receptor." (PMID 23029153, 2012).
Hypertension (4 papers, 2012 to 2026). The presence of chronic increased pressure in the systemic arterial system. "Extending these observations beyond ischemic remodeling, a biased small-molecule FPR1/2 agonist (compound 17b; Cmpd17b) has also been shown to mitigate hypertension-driven CV injury in an angiotensin II—induced model." (PMID 41516407, 2026). "We have found a link of FPR1 over-expression and FPR2 under-expression on blood neutrophil along with defective production of LXA4/RvD1, as well as FPR3 insufficiency of M1 monocyte, M2a monocyte, and NK cell, to OSA and its adverse consequences, including hypertension and EDS." (PMID 31116781, 2019). "Furthermore, we found increased FPR1/FPR2 ratio and insufficiency of FPR2 and FPR3 in the OSA patients with EDS and hypertension phenotypes, respectively, while long-term CPAP treatment decreased FPR1 expression and FPR1/FPR2 expression ratio, and increased FPR3 and FPR2 expression." (PMID 31116781, 2019).
meningitis (4 papers, 2008 to 2024). A disorder characterized by acute inflammation of the meninges of the brain and/or spinal cord. "Finally, we were interested whether the meningitis-induced astrocyte and microglia response are ameliorated in Ac2-26-treated Fpr1−/− and Fpr2−/− mice." (PMID 33121515, 2020).
pneumococcal meningitis (4 papers, 2015 to 2024). An acute purulent infection of the meninges and subarachnoid space caused by Streptococcus pneumoniae, most prevalent in children and adults over the age of 60. "Formyl peptide receptor (FPR)-1 or -2 deficient mice had higher bacterial titers than wild-type mice after pneumococcal meningitis, and wild-type mice lived significantly longer than both knockout strains." (PMID 25958220, 2015). "Our earlier results demonstrated that the anti-inflammatory properties of Ac2-26 in a model of pneumococcal meningitis are mediated via FPR2 but not FPR1." (PMID 39768195, 2024).
acute respiratory distress syndrome (3 papers, 2017 to 2021). Progressive and life-threatening pulmonary distress in the absence of an underlying pulmonary condition, usually following major trauma or surgery. "In acute respiratory distress syndrome (ARDS), elevated mitochondrial formylated peptides induced sterile acute lung inflammation and injury through FPR1 signaling, thereby suggesting a potential new therapeutic target in ARDS." (PMID 30356317, 2018). "FPR-1 knocks out and FPR-1 antagonist attenuated this inflammation process of acute lung injury; FPR-1 may be a novel therapeutic target for acute respiratory distress syndrome through the regulation of inflammation." (PMID 33981222, 2021).
Arthritis (3 papers, 2018 to 2025). Inflammation of a joint. "Notably, activation of FPR2 and the homologue receptor FPR1 has shown therapeutic benefit against disease symptoms in K/BxN serum transfer-induced arthritis (STIA)." (PMID 40181186, 2025). "Previously, treatment of cpd43 (a dual agonist of FPR1 and FPR2) has been reported to decrease clinical severity in the K/BxN serum-transfer arthritis model." (PMID 30279454, 2018).
bacterial meningitis (3 papers, 2020 to 2021). Inflammation of the membranes surrounding the brain and spinal cord due to a bacterial infection. "We and others have previously shown that the expression of both, Fpr1 and Fpr2, is altered in various inflammatory and neurodegenerative animal models including APP/PS1 double-transgenic, in a model of acute, metabolic oligodendrocyte injury, or in a model of bacterial meningitis." (PMID 32331524, 2020). "In summary, this study demonstrates anti-inflammatory properties of Ac2-26 in a model of bacterial meningitis, which are mediated via FPR2, but not FPR1." (PMID 33121515, 2020).
bronchiolitis obliterans syndrome (3 papers, 2020 to 2023). A lung disorder that is mainly associated with chronic allograft dysfunction after lung transplantation and that is characterized by inflammation and fibrosis of bronchiolar walls that reduce the diameter of the bronchioles and result in progressive and irreversible airflow obstruction. "Some chronic inflammatory conditions, such as endometriosis, bronchiolitis obliterans syndrome, etc. have been shown to regulate NLRP3 inflammasome via the Formyl Peptide Receptor 1 (Fpr-1)-mediated signaling pathway." (PMID 32842536, 2020).
chronic obstructive pulmonary disease (3 papers, 2011 to 2024). A chronic and progressive lung disorder characterized by the loss of elasticity of the bronchial tree and the air sacs, destruction of the air sacs wall, thickening of the bronchial wall, and mucous accumulation in the bronchial tree. "For example, FPR1 expression is increased in peripheral neutrophils of patients with chronic obstructive pulmonary disease and emphysema." (PMID 38351296, 2024).
colorectal tumors (3 papers, 2017 to 2022). "CCR2 and FPR1 are overexpressed in colorectal tumours, while Bacteroidales are enriched in CRC and associated with tumorigenesis." (PMID 35577971, 2022). "In related studies on colorectal tumors, FPR1 mRNA expression has been confirmed to be related to tumor serous membrane infiltration, and FPR1 protein is expressed in colorectal epithelium and tumor-infiltrating neutrophils/macrophages." (PMID 33603656, 2021). "In this work, we found that the expression of FPR1, but not FPR2 or FPR3, was associated with colorectal tumor serosal invasion." (PMID 28724995, 2017). "The levels of FPRs mRNA, especially those of FPR1, were significantly higher in colorectal tumors than in distant normal tissues and adjacent non-tumor tissues." (PMID 28724995, 2017). "We found that the mRNA level of FPRs, especially that of FPR1, was significantly higher in colorectal tumors than in distant normal tissues and adjacent non-tumor tissues." (PMID 28724995, 2017). "We found that the mRNA levels of FPRs, especially those of FPR1, were significantly higher in colorectal tumors than in distant normal tissues and adjacent non-tumor tissues (p < 0.05)." (PMID 28724995, 2017).
endometriosis (3 papers, 2018 to 2021). The growth of functional endometrial tissue in anatomic sites outside the uterine body. "We underline the pathogenic role of Fpr1 in experimental endometriosis, which is the result of modulation of immune cell recruitment, suggesting it as a new target to control the pathologic features of endometriotic lesions." (PMID 30140375, 2018). "FPR-1 gene deletion has been reported to take protective effects via the downregulation of the NF-κB pathway in surgically induced endometriosis." (PMID 33981222, 2021). "We investigated the development of the physiopathology of the surgically-induced endometriosis in Fpr1 KO mice compared to WT animals." (PMID 30140375, 2018). "Tissues from Fpr1 KO mice exhibited a reduced IkBα degradation and NF-κB translocation to the nucleus induced by endometriosis." (PMID 30140375, 2018). "Collectively, the data shows that animals with a deletion of Fpr1 gene displayed reduced inflammation and pain induced by an experimental mouse model of endometriosis, suggesting it as a new target to control the pathologic features of endometriotic lesions." (PMID 30140375, 2018). "In particular it has been described the up-regulation of the Fpr1 in patients affected by endometriosis and its role in cell differentiation and proliferation." (PMID 30140375, 2018). "The current work demonstrates that the altered Fpr1 gene expression profile allows endometriotic lesion regression in an autologous mouse model of surgically-induced endometriosis." (PMID 30140375, 2018).
ischemic stroke (3 papers, 2022 to 2024). A stroke disorder caused by obstruction of blood flow to the brain, due to thrombotic (local blood clot formation) or embolic (due to a blood clot or other material traveling from another site) event. "Among these DEGs, it has been reported that the upregulation of FPR1 following ischemic stroke is closely associated with secondary neurological deficits and neuroinflammatory responses." (PMID 39654367, 2024). "FPR1 antagonists have been shown to inhibit peripheral monocyte migration into the brain, thereby ameliorating neuroinflammation post‐ischemic stroke." (PMID 39654367, 2024). "cFLFLF did not affect the proinflammatory cytokine levels in the spleen and brain of fpr1-/- mice after ischemic stroke." (PMID 35547761, 2022). "Results: cFLFLF, a FPR1 antagonist, inhibited splenocyte migration into the brain and neuroinflammation after ischemic stroke." (PMID 35547761, 2022). "Finally, we explored the involvement of the FPR1/NLRP3 axis in both LPS‐induced neuroinflammation and ischemic stroke models in mice." (PMID 39654367, 2024).
osteosarcoma (3 papers, 2016 to 2025). A usually aggressive malignant bone-forming mesenchymal neoplasm, predominantly affecting adolescents and young adults. "Herein, we show that the cyclization of the uPAR88–92 sequence generates a potent inhibitor of migration, and extracellular matrix invasion of human osteosarcoma and chondrosarcoma cells expressing comparable levels of FPR1 on cell surface." (PMID 27323409, 2016). "In this study, we present evidence that the cyclization of the uPAR88–92 sequence generates a new potent inhibitor of migration, and extracellular matrix invasion of human osteosarcoma and chondrosarcoma cells expressing comparable levels of FPR1 on cell surface." (PMID 27323409, 2016).
peritonitis (3 papers, 2016 to 2025). Inflammation of the peritoneum (tissue that lines the abdominal wall and covers most of the organs in the abdomen). "In this study, we evaluate the effects of the Fpr1 and Fpr2 agonists Ac9-12 and WKYMV, respectively, in carrageenan-induced acute peritonitis and LPS-stimulated macrophages." (PMID 35053343, 2022).
acute lymphoblastic leukemia (2 papers, 2016 to 2020). Leukemia with an acute onset, characterized by the presence of lymphoblasts in the bone marrow and the peripheral blood. "Additionally, Szczepanek and co-authors demonstrated that FPR1 expression is associated with drug resistance in patients with acute lymphoblastic leukemia." (PMID 27432059, 2016).
Anxiety (2 papers, 2014 to 2023). Intense feelings of nervousness, tension, or panic often arise in response to interpersonal stresses. "Interestingly, FPR1 loss-of-function is associated with reduced anxiety and fear behaviors, suggesting that FPR1 and FPR2 receptors serve complementary roles." (PMID 37483341, 2023). "Recent findings indicate that the centrally regulated behaviours of anxiety and fear-elicited responses are strongly modulated by FPR1." (PMID 25517119, 2014).